PRKN (parkin RBR E3 ubiquitin protein ligase)
Diseases named in the same sentence as PRKN in open-access papers (continued):
Sharing a sentence is not in itself a finding about the gene and the disease.
Dyskinesia (18 papers, 2010 to 2025). A movement disorder which consists of effects including diminished voluntary movements and the presence of involuntary movements. "As far as the presence of motor complications is concerned, 9/13 of PRKN mutation carriers exhibited motor fluctuations and/or dyskinesias during their disease course." (PMID 39195564, 2024). "We suggest that other variants in PRKN or in other mitophagy genes may participate in the development of levodopa-induced dyskinesia in PD treatment." (PMID 37626726, 2023). "The phenotype of PRKN variants is characterized by a benign course with slow progression, a favorable response to levodopa or anticholinergic medications, common presentation as dystonia, especially in the lower extremities, and the frequent emergence of dyskinesias and motor fluctuations." (PMID 39195564, 2024). "49% (45/91) of PRKN-PD patients had developed dyskinesias, with half developing it by 19 years, compared to half developing it by 9 years in early-onset PD." (PMID 38553467, 2024). "Our results reinforce that age at onset of symptoms, duration of PD, and treatment and dosage of LD can influence the occurrence of dyskinesia but not the investigated PRKN variants." (PMID 37626726, 2023). "According to previously published data, PD patients harboring PRKN mutations require a low LEDD for excellent control of motor signs, but despite receiving markedly low doses of levodopa, they exhibited the frequent development of motor complications and dyskinesias from early disease stages." (PMID 39195564, 2024). "Thus, in the present study, the distribution of 14 variants in the PRKN gene of the mitophagy pathway was investigated in a cohort of PD patients undergoing treatment with LD, divided into individuals with and without dyskinesia." (PMID 37626726, 2023). "However, a study demonstrated that individuals with certain PRKN mutations have a better response to LD treatment, although they are possibly at a higher risk of developing dyskinesia compared to individuals without these PRKN mutations." (PMID 37626726, 2023). "The case presented a PRKN/PINK1‐related EOPD with a lower AAO, slower development, early dyskinesia, and a favorable response to levodopa and STN DBS." (PMID 40898742, 2025). "However, it’s vital to consider potential complications that may occur upon DBS implantation, including cognitive decline and dyskinesias such as seen in SNCA, GBA and PRKN-PD." (PMID 39619277, 2024). "PRKN and PINK1 mutation carriers also reported more postural problems at diagnosis than non-carriers and tended to report a higher rate of dyskinesias, after adjusting for age at entry, gender, disease duration and LEDD total, although this did not survive correction for multiple testing." (PMID 31324919, 2019).
glioblastoma (18 papers, 2011 to 2025). The most malignant astrocytic tumor (WHO grade IV). "However, PRKN has been widely described as a tumor suppressor, with loss-of-function mutations arising in a variety of cancers, including glioblastomas." (PMID 40612515, 2025).
autism (17 papers, 2013 to 2025). Persistent deficits in social interaction and communication and interaction as well as a markedly restricted repertoire of activity and interest as well as repetitive patterns of behavior. "Most other “pathogenic” and “likely pathogenic” CNVs do not overlap nor appear similar to CNVs listed in Decipher, but they do span “autism genes” listed in the SFARI GENE, and AutismKB databases, such as DMD, NEXMIF, NLGN4X, PRKN, and others." (PMID 35762097, 2022).
melanoma (17 papers, 2011 to 2025). A malignant, usually aggressive tumor composed of atypical, neoplastic melanocytes. "PRKN mutations were also identified in melanoma cases, and its expression level was found to decrease in melanoma cell lines." (PMID 32210791, 2020). "In melanoma with BRAF/NRAS mutations, PRKN is downregulated, while BRAFV600E or MAPK inhibition can increase PRKN expression leading to cytostatic and apoptotic effects." (PMID 40862737, 2025). "Expression of PRKN in melanoma cells attenuated cell proliferation and conversely, inhibition of PRKN in melanocytes induced cell proliferation." (PMID 32210791, 2020). "In summary, our meta-analyses of 147 acral and 93 mucosal melanomas identified PTPRJ, FER, SKP2, LZTR1, CIC, and PRKN as part of a long tail of driver events that deserves further study and characterization." (PMID 35706047, 2022).
diabetes (16 papers, 2013 to 2025). "Although epidemiologic studies on the association between diabetes and PRKN gene alterations are limited, the study noted an increased frequency of diabetes in heteroplasmy PRKN variant carriers." (PMID 39835172, 2025). "Interestingly, a higher percentage of heterozygous PRKN mutation carriers manifest diabetes mellitus (p = 0.023), which is known to be associated with PD risk in multiple population-based prospective studies." (PMID 34434164, 2021). "Notably, diabetes was associated with the heterozygous PRKN mutation carrier status in our study." (PMID 34434164, 2021). "The miR-181c levels of elderly patients with frailty who present with diabetes mellitus and heart failure with preserved ejection fraction were significantly high, and miR-181c targeted PRKN and SMAD7 in human cardiac fibroblasts." (PMID 39444490, 2024).
Sepsis (16 papers, 2020 to 2025). Sepsis is defined as life-threatening organ dysfunction caused by a dysregulated host response to infection. "Furthermore, PINK1 and PARK2 (parkin RBR E3 ubiquitin protein ligase) exhibit neuroimmunoprotective effects in sepsis." (PMID 40766066, 2025).
colon cancer (13 papers, 2013 to 2025). "A study identified DNA copy number loss of PRKN (PARK2 gene) in about 33% of the colon tumors screened." (PMID 34138755, 2021). "For example, the PRKN gene and human colorectal cancer are obviously associated with adenomatous polyps, and the expression of PRKN can inhibit the proliferation of colon cancer cells." (PMID 33262988, 2020). "The mutation or depletion of PINK1 or PRKN is often detected in a variety of tumors, such as lung cancer, glioma, and colon cancer." (PMID 33262988, 2020). "While there are implications for PRKN-mediated mitophagy in CRC, one study found around 33% of colon tumors harbor PARK2 (the gene that encodes for PRKN) DNA copy number loss." (PMID 31671556, 2019). "The hybridization of PRKN knockout mice with colorectal adenomatous polyposis mice significantly accelerates the development of intestinal adenomas in newborn mice, and the diversity of polyps is also significantly increased, indicating that PRKN is a tumor suppressor gene in colon cancer." (PMID 33262988, 2020).
Cognitive impairment (12 papers, 2011 to 2025). Abnormal cognition is characterized by deficits in thinking, reasoning, or remembering. "Intriguingly, we showed that those three out of five patients carrying PRKN variants had cognitive impairment (MoCA score less than 26), which was unusual as other findings." (PMID 36879366, 2023). "On the other hand, CASI therapy may be beneficial in the PRKN mutation carriers, especially when severe cognitive impairment is known to be rare in this group of patients." (PMID 35754954, 2022). "This is consistent with previous studies showing that PRKN and PINK1 mutations are generally associated with slower disease progression and less cognitive impairment." (PMID 31324919, 2019). "Carriers of the G2019 variant in LRRK2 and PRKN mutations showed sustained advantages in motor complications and activities of daily living, whereas GBA mutation carriers frequently developed cognitive impairment and stimulation-resistant symptoms within 2 to 7 years after surgical treatment." (PMID 30707228, 2019). "However, we did find that PRKN and PINK1 mutation carriers have distinctive clinical features compared to young-onset non-carriers, with more postural symptoms at diagnosis and less cognitive impairment, after adjusting for age and disease duration." (PMID 31324919, 2019). "PRKN-related PD non-motor symptoms resemble those of PD noncarriers with less autonomic and cognitive impairment." (PMID 36291241, 2022).
colorectal cancer (12 papers, 2016 to 2025). A primary or metastatic malignant neoplasm that affects the colon or rectum. "Tanshinone IIA inhibits mitophagy and enhances apoptosis in colorectal cancer cells by inhibiting the PRKN pathway." (PMID 39723259, 2024). "Loss of PRKN is a feature of some BRAF mutant cell lines and it is also, rarely, encountered in BRAF mutant colorectal cancers." (PMID 36295658, 2022). "These cell lines and the cell line NCI-H508 also possess deletions of PRKN, encoding for ubiquitin ligase parkin, which is the only recurrent deletions in BRAF/PIK3CA double mutant colorectal cancer cell lines." (PMID 36295658, 2022). "Besides BRAF mutations, BRAF inhibitor sensitivity in colorectal cancer cell lines is conferred by SACS mutations and PRKN locus loss." (PMID 36295658, 2022).
dementia (11 papers, 2007 to 2025). Loss of intellectual abilities interfering with an individual's social and occupational functions. "Specifically, dementia is rare in PD with PRKN mutations, and less common in PD with LRRK2 mutations than in the idiopathic form." (PMID 40722695, 2025). "Moreover, our results on the absence of dementia are compatible with literature concerning PRKN and PINK1 mutations although there are some exceptions notably for PINK1 carriers." (PMID 39195564, 2024). "In terms of enrichment in the Jessen disease database, acrodysostosis (padjusted = 0.068) and dementia (padjusted = 0.068) were the most relevant diseases, involving PDE4D, Sortilin Related Receptor 1 (SORL1) and Parkin RBR E3 Ubiquitin Protein Ligase (PARK2) genes." (PMID 41473159, 2025). "In our NGS study, we identified RDVs in genes which were previously associated with other neurodegenerative disorders with or without dementia, such as C19ORF12, PRKN, LRRK2, and PARK7 genes in three patients (P81, P35, P50)." (PMID 35752680, 2022).
Insulin resistance (10 papers, 2019 to 2025). Increased resistance towards insulin, that is, diminished effectiveness of insulin in reducing blood glucose levels. "siRNA-mediated knockdown of PRKN and PINK1 abrogated the TAC-induced reduction in hepatic insulin resistance." (PMID 37151651, 2023).
schizophrenia (10 papers, 2011 to 2024). A major psychotic disorder characterized by abnormalities in the perception or expression of reality. "Previous studies reported that carriers of digenic variants in PRKN and PINK1 develop the disease at a younger age and exhibit distinctive symptoms such as schizophrenia, facial dyskinesia, grimacing and severe dysarthria and also epilepsy and essential tremor." (PMID 38173558, 2023).
ovarian cancer (9 papers, 2015 to 2025). A primary or metastatic malignant neoplasm involving the ovary. "The PINK1 and PRKN enrichment was observed with the conversion of LC3-I to LC3-II in the mitochondrial fraction of pyrimethamine-treated ovarian cancer cells in a dose-dependent manner." (PMID 40918465, 2025). "Although the canonical PINK1/PRKN (parkin RBR E3 ubiquitin protein ligase) pathway showed weak effects in ovarian cancer, PINK1 was identified to interact with PTEN and phosphorylate it at Serine179." (PMID 37940999, 2023). "To exemplify the power of NeDRex to extract biologically meaningful pathways from starting seeds, we used the ovarian cancer (OC) associated genes from NeDRexDB (AKT1, ALPK2, CDH1, CTNNB1, EPHB1, OPCML, PIK3CA, PRKN) and constructed disease module using the MuST algorithm." (PMID 34824199, 2021).
pancreatic cancer (9 papers, 2019 to 2025). "The depletion of PRKN also enhanced pancreatic tumorigenesis in KRAS-driven engineered mouse models based on its role in mediating the degradation of mitochondrial iron importers, implying that PRKN can be a potential target for pancreatic cancer therapy." (PMID 31921812, 2019). "Additionally, the usefulness of a three-gene signature (PRKN, SRC and VDAC1) was evaluated based on genes related to mitophagy to predict survival in pancreatic cancer patients." (PMID 38048216, 2023). "Consequently, in vitro or xenograft mouse models show that the genetic depletion of STING1 or MFN1/2 (but not the mitophagy regulator PINK1 or PRKN) reduces the sensitivity of pancreatic cancer cells to ferroptosis." (PMID 34195205, 2021).
chronic obstructive pulmonary disease (7 papers, 2016 to 2025). A chronic and progressive lung disorder characterized by the loss of elasticity of the bronchial tree and the air sacs, destruction of the air sacs wall, thickening of the bronchial wall, and mucous accumulation in the bronchial tree. "In contrast, mitophagy protein PINK1 cannot eliminate the effects of PRKN, which indicates that mitophagy protein PRKN plays a key role in regulating mitochondrial autophagy and the pathogenesis of chronic obstructive pulmonary disease (COPD)." (PMID 35321239, 2022).
depression (7 papers, 2011 to 2026). "Clinical assays targeting processes relevant to the molecular functions of PRKN might provide new avenues for the early or more accurate detection of depression." (PMID 40559334, 2025). "CONCLUSIONS: PRKN-PD is characterized by widespread serotonergic dysfunction, which is independent of dopaminergic degeneration and linked to key non-motor symptoms, particularly depression." (PMID 41606302, 2026). "The hypokinetic/rigid picture seems to be in line with what is reported in the literature about PRKN and GBA1 mutations, while the important anxiety–depressive syndrome follows the non-motor symptomatology often associated with GBA1." (PMID 40141040, 2025).
Hepatic steatosis (7 papers, 2019 to 2025). Steatosis is a term used to denote lipid accumulation within hepatocytes. "Furthermore, activation of PRKN-mediated mitophagy may mitigate hepatic steatosis by activation of lipophagy in animal models of binge ethanol exposure." (PMID 37007026, 2023).
Huntington disease (7 papers, 2016 to 2025). Huntington disease (HD) is a rare neurodegenerative disorder of the central nervous system characterized by unwanted choreatic movements, behavioral and psychiatric disturbances and dementia. "Our data mining result points thus to a yet unnoticed property of PRKN as a major hub protein connecting a large array of proteins involved in not only PD but also ALS, AD, Huntington's disease and/or FTD." (PMID 31824497, 2019).
neuroblastoma (7 papers, 2015 to 2026). Neuroblastoma (NB) is the most common solid, extracranial childhood tumor. "Here, we reported multiple instances of predicted PRKN loss of function in patients with Wilms, CNS, neuroblastoma, and osteosarcoma tumors." (PMID 32371905, 2020). "Germline loss of function of the PRKN gene was frequently found in our patients with Wilms, CNS, neuroblastoma, and osteosarcoma tumors." (PMID 32371905, 2020). "PINK1 and PRKN (encoding PARKIN) get transcriptionally induced in human neuroblastoma cells after serum deprivation or nutrient starvation, linking dietary restriction to mitophagy." (PMID 33023155, 2020).
cognitive decline (6 papers, 2020 to 2025). "Genetics can impact the risk level for cognitive decline; PRKN is associated with relatively lower risk of cognitive decline and dementia." (PMID 41410819, 2025). "Notably, a large multicenter study reported cognitive decline in 25%, which is a percentage higher than that for PRKN mutation carriers." (PMID 40722695, 2025).
synucleinopathy (6 papers, 2009 to 2024). A neurodegenerative disease that is characterized by the abnormal accumulation of aggregates of alpha-synuclein protein in neurons, nerve fibers or glial cells. "Notably, some genetic traits associated with increased PD risk, such as LRRK2 and PRKN pathogenic variants, are associated with lower likelihood of both olfactory loss and underlying alpha-synucleinopathy." (PMID 39434044, 2024). "Furthermore, tauopathies were observed in PD patients with RAB39B and PRKN mutations prior to the development of synucleinopathies, suggesting that tau accumulation may be upstream of α-syn aggregates." (PMID 38751879, 2024). "For AR-PD patients, α-syn deposition was observed in both skin biopsies and brain autopsies in DJ-1-mutant PD patients, whereas synucleinopathy was observed only in brain autopsies in PRKN-mutant PD patients." (PMID 38751879, 2024). "PD patients with PRKN and RAB39B mutations commonly exhibited α-syn (synucleinopathy) and AT8 (p-tau) positivity." (PMID 38751879, 2024). "However, there was a significant difference in synucleinopathies between the PRKN-related PD patients and brain autopsies." (PMID 38751879, 2024). "Patients with SNCA, LRRK2, or GBA variants have peripheral synucleinopathy, while patients with PRKN variants do not." (PMID 35395825, 2022). "However, despite the absence of Lewy pathology, synucleinopathies have still been observed in brain autopsies of older PD patients with PRKN mutations." (PMID 38751879, 2024). "In conclusion, our study of peripheral cutaneous synucleinopathy characteristics in patients with genetic PD yielded several key findings: (i) P-α-syn was deposited in the peripheral cutaneous nerves of PD patients with CHCHD2, LRRK2, or GBA mutations but not in those with RAB39B or PRKN mutations." (PMID 38751879, 2024).
myeloma (5 papers, 2017 to 2024). "The levels of the PINK1‐dependent mitophagy markers PINK1 and parkin RBR E3 ubiquitin protein ligase (PARK2) in CD138+ plasma cells are reduced in patients with MM and correlate with clinical outcomes in myeloma patients." (PMID 32154065, 2020).
prostate carcinoma (4 papers, 2013 to 2024). A carcinoma that arises from epithelial cells of the prostate gland. "Second, we engineered syngeneic murine prostate cancer TRAMP-C2 cells to transiently or conditionally (TetON system) express PRKN mRNA and protein." (PMID 39213189, 2024). "For these experiments, we engrafted prostate cancer TRAMP-C2 cells onto the flanks of C57BL/6J mice and treated the animals with decitabine, which restores PRKN expression and associated IFN gene expression." (PMID 39213189, 2024). "However, loss of PRKN in these mice was associated with early onset prostate cancer formation at 26 weeks of age, when no tumors were detected in TRAMP mice of comparable age." (PMID 39213189, 2024). "A similar response was observed in murine prostate cancer cell types MPTEN1 and MP3098, where transient reintroduction of PRKN potently upregulated IFN gene expression." (PMID 39213189, 2024). "Consistent with this, reexpression of PRKN in prostate cancer DU145 or pancreatic adenocarcinoma PANC-1 cells increased IFN-γ mRNA levels, whereas PRKN siRNA silencing in MCF10A cells suppressed IFN-γ expression." (PMID 39213189, 2024).
breast tumors (3 papers, 2020 to 2025). "For example, the effects of higher pathway activity scores found in breast tumors expressing low levels of PRKN was quite evident." (PMID 39859167, 2025).
developmental delay (3 papers, 2020 to 2025). "Case 15 is a child with developmental delay and behavioral/psychiatric decline that met PANS criteria, who has a de novo PRKN exon 2/3 deletion." (PMID 40894167, 2025).
lung adenocarcinoma (3 papers, 2017 to 2025). A carcinoma that arises from the lung and is characterized by the presence of malignant glandular epithelial cells. "In addition, PRKN was markedly downregulated in lung adenocarcinoma (LUAD), colon adenocarcinoma (COAD), thyroid cancer (THCA), and lung squamous cell carcinoma (LUSC), respectively." (PMID 39859167, 2025). "In addition, PRKN, PINK1 and MAP1LC3A, expression levels were positively correlated with the infiltration score, as well as the infiltration of various immune cells, including iTreg, effector memory, exhausted, Th1, and nTreg cells in lung adenocarcinoma (LUAD)." (PMID 39859167, 2025).